MMP1 (matrix metallopeptidase 1)
Diseases named in the same sentence as MMP1 in open-access papers (continued):
Sharing a sentence is not in itself a finding about the gene and the disease.
colorectal cancer (continued). "The overexpression of MMP-1 mRNA has been demonstrated in a variety of cancers such as gastric cancer, colorectal cancer and esophageal cancer." (PMID 24505369, 2014). "We investigated the role of MMP1, MMP3 and MMP7 promoter polymorphisms as colorectal cancer risk factors in a case-control study of cases with large adenomatous polyps (n = 295), versus small adenomatous polyps cases (n = 302) or PF controls (n = 568)." (PMID 17125518, 2006). "MMP1 has been reported to exhibit oncogenic roles in various malignant tumors, including Uveal melanoma, Liver cancer, Cervical squamous cell carcinoma and Colorectal Cancer." (PMID 40666104, 2025). "Although the mechanistic link between CD26 inhibition and metastatic suppression was not directly explored in this study, previous reports suggest that CD26 may promote metastasis through the CAV1/MMP1 signaling axis in colorectal cancer." (PMID 40806753, 2025). "MMP1 had been previously identified as a promising therapeutic target in colorectal cancer." (PMID 38528462, 2024). "Our results supported this contention and indicated that Famciclovir could have an anti-cancer effect in colorectal cancer by inhibiting MMP1 expression in HT-29, according to qRT-PCR result." (PMID 38528462, 2024). "In colorectal cancer, MMP1 promotes cancer cell growth by stimulating the cell cycle." (PMID 38580797, 2024). "Moreover, CHRM3 activation significantly promotes colorectal cancer invasion via enhanced cellular release of MMP1." (PMID 37744266, 2023). "Next, we examined whether targeting JNK by SP600125 affects the expression of MMP-1 in colorectal cancer cells." (PMID 36207462, 2022). "Next, we performed wound healing assay to investigate whether overexperesson of MMP-1 reduces the inhibitory effects of CAMSAP2 shRNAs on colorectal cancer cell migration." (PMID 36207462, 2022). "In summary, our study revealed that CAMSAP2 promoted the migration, invasion and metastasis of colorectal cancer cells through activation of JNK/c-Jun/MMP-1 signaling pathway, suggesting CAMSAP2 is a potential therapeutic target for metastatic colorectal cancer." (PMID 36207462, 2022). "Therefore, the specific mechanism of action of MMP3 and MMP1 in colorectal cancer needs to be further studied." (PMID 36338624, 2022). "Next, we asked how CAMSAP2 regulates MMP-1 in colorectal cancer cells." (PMID 36207462, 2022). "Additionally, upon treatment with SP600125, the promoter activity of MMP-1 induced by CAMSAP2 upregualtion was inhibited in both tested cell lines of colorectal cancer." (PMID 36207462, 2022). "It has been shown that MMP1 is regulated by the p38 MAPK signaling pathway in colorectal cancer." (PMID 31001480, 2019). "Alternatively, the inverse relationship between IPC and the high-expressing MMP-1 2G/2G genotype may reflect linkage disequilibrium between the MMP-1 2G and MMP-3 6A alleles as has been reported in colorectal cancer." (PMID 17922906, 2007). "Therefore, we hypothesized that CAMSAP2 may regulate MMP-1 transcription in colorectal cancer cells by stimulating JNK/c-Jun signaling pathway." (PMID 36207462, 2022). "However, the downregulation of MMP‐1 expression inhibited the progression of colorectal cancer, it could thus be speculated that baicalein could slow down the progression of colorectal cancer by inhibiting MMP-1 expression." (PMID 34125845, 2021). "In IPF, SPP1+ macrophages are highly expanded in fibrotic lesions and cross talk with myofibroblasts to drive fibrotic changes; in colorectal cancer, there are direct interactions between SPP1+ macrophages and FAP+ fibroblasts expressing high levels of MMP1/3." (PMID 41489684, 2026). "In our experimental conditions, blueberry pomace extract most effectively inhibited MMP-1, MMP-2, and MMP-3 in C2BBe1 colorectal cancer cells." (PMID 39200479, 2024).
colorectal cancer (continued). "In this study, we conducted differential gene expression analysis on three GEO datasets and confirmed SPP1, MMP1, CXCL8, CXCL1, TIMP1, MMP3, and CXCL10 as core regulatory genes in colorectal cancer through a protein-protein interaction network." (PMID 37842645, 2023). "Taken together, our results confirmed that CAMSAP2 enhanced the expression of MMP-1 through activation of JNK/c-Jun signaling pathway, and thereby promoted the migration and invasion of colorectal cancer cells." (PMID 36207462, 2022). "In the current investigation, our data illustrated the overexpression of MMP-1 in CRC specimens, which confirmed the oncogenic role of MMP-1 in colorectal cancers." (PMID 35456495, 2022). "Treatment with Rh2 (10 μM) hindered expression of three types of MMPs, MMP-1, MMP-2 and MMP-9 in HCT116 and SW620 human colorectal cancer cells via regulation of JAK2 and STAT3 pathways." (PMID 33671187, 2021). "We revealed that quercetin, stigmasterol, kaempferol, baicalein, and acacetin played a critical role in colorectal cancer by affecting PTGS2, NR3C2, CA2, and MMP1." (PMID 34125845, 2021). "A previous pan-cancer single cell analysis of ovarian, lung, and colorectal cancer, showed that COMP, COL10A1, COL11A1, and MMP1 all have higher expression in CAFs26." (PMID 34732773, 2021). "In addition, several Matrix Metalloproteinases (MMPs) such as MMP1 or MMP7, which regulate cancer invasiveness by modulating extracellular matrices degradation are regulated by high levels of ETV1 in prostate and colorectal cancers." (PMID 40275610, 2025). "In the phase of adenoma development, increased expression of MMP-1, MMP-3, MMP-7, and MMP-9 was observed, and subsequently, at the stage of colorectal cancer invasion, other MMPs, including MMP-2, MMP-8, MMP-10, MMP-12, MMP-13, MMP14, and MMP-21 are activated and overexpressed." (PMID 39337393, 2024). "Currently, evidence is accumulating that the ERK1/2/MMP-1 axis could inhibit metastasis of human oral squamous cells, and that knocking down of MMP-1 could suppress the PI3K/Akt/c-myc signaling pathway and EMT in colorectal cancer." (PMID 36839884, 2023). "CRP could potentially promote CEA, MMP1 and MMP2 by stimulating LOX-1 receptors in colorectal cancer." (PMID 38071306, 2023). "In addition, transwell migration and invasion assays also showed that silencing MMP-1 inhibited the migration and invasion induced by CAMSAP2 in both tested colorectal cancer cells." (PMID 36207462, 2022). "In addition, in colorectal cancer and ESCC, the overexpression of MMP1 promoted cell proliferation, migration, invasion, EMT in vitro, and metastasis in vivo." (PMID 36105241, 2022). "Taken together, our findings demonstrated that CAMSAP2 promoted colorectal cancer cell migration, invasion and metastasis through activation of JNK/c-Jun/MMP-1 signaling pathway, indicating CAMSAP2 is a promising therapeutic target for the treatment of metastatic colorectal cancer patients." (PMID 36207462, 2022). "Research shows that the expression of MMP-1 in colorectal cancer tissues is higher than that in normal colon tissues, and MMP-1 may influence the occurrence and development of colorectal cancer through EMT and Akt signaling pathways." (PMID 34125845, 2021). "Metastatic abilities of SW620 colorectal cancer cells were also suppressed by Rh1 (100 μM) via inhibition of MAPK signaling transduction pathways and transcriptions of MMP-1 and MMP-3 while increasing expression of tissue inhibitor of metalloproteinases 3 (TIMP3), a negative regulator of MMPs." (PMID 33671187, 2021). "MLK3 appears to function as an oncogene to promote cell migration and invasion through the MLK3/JNK pathway in human breast and gastric cancer cells, the MLK3/FRA-1/MMP-1 axis in human triple-negative breast cancer cells, or MLK3/ERK signaling in ovarian and colorectal cancer cells." (PMID 33692940, 2020).
colorectal cancer (continued). "This is a clear indication that MMP-2 is a key factor in the regulation of cell migration, however it should not be ruled out that other ECM degrading MMPs such as MMP-1, MMP-7, MMP-9 and MMP-13 have been shown be associated with Colorectal cancer progression." (PMID 24130681, 2013). "In addition, MMP1, MMP3 and MMP9 polymorphisms were not linked with colorectal cancer susceptibility." (PMID 28445160, 2017). "Expression of MMP-1 and MMP-7 was elevated in patients with primary colorectal cancer with or without liver metastasis." (PMID 34502094, 2021).
periodontitis (59 papers, 2013 to 2026). An acute or chronic inflammatory process that affects the tissues that surround and support the teeth. "ROC analysis assessed diagnostic accuracy, logistic regression pinpointed risk factors for stage III/IV periodontitis, and ELISA measured levels of inflammatory cytokines and MMP-1/MMP-3Cell viability and apoptosis were assessed by CCK-8 and flow cytometry." (PMID 41820893, 2026). "Some studies suggest an association between genetic polymorphisms of IL-1 and IL-4 coding genes and MMP-1 gene promoter and periodontitis in CKD patients." (PMID 39652270, 2025). "Elevated levels of HG-EMMPRIN are associated with the increased production of active MMP-1 and proMMP-1, which are key mediators of tissue breakdown in chronic periodontitis." (PMID 40075856, 2025). "In experimental models of periodontitis in rats, Kaempferol reduced the alveolar bone resorption, inhibiting the attachment loss and MMP-1 production." (PMID 40004956, 2025). "Remarkably, significant associations have been found between MMP‐1, 3, and 7 gene polymorphisms and the incidence of chronic periodontitis." (PMID 39610026, 2024). "Of metalloproteinases, polymorphisms of the MMP-1 encoding gene were most frequently assessed in relation to periodontitis." (PMID 35454140, 2022). "Lastly, since tissue destruction associated with periodontitis is mostly mediated by MMPs, we evaluated the effect of Daiokanzoto on the catalytic activity of MMP-1 and MMP-9, which are secreted by several human cell types." (PMID 26859747, 2016). "Several polymorphisms in the MMP-1 gene resulting in a constitutive active form of the proteinase were shown to coincide with severe forms of periodontitis." (PMID 25861162, 2015). "Our meta-analysis demonstrated that MMP-1 g.-1607dupG polymorphism was associated with chronic periodontitis, especially the severity of the disease condition." (PMID 23527212, 2013). "Although multiple studies had focused on the association between MMP-1 g.-1607dupG and periodontitis susceptibility, the results remained inconclusive." (PMID 23527212, 2013). "Retrieved studies from Pubmed, Web of Science, Medline and Google Scholar Search regarding MMP-1 g.-1607dupG and periodontitis susceptibility were included into the final analysis with definite selection and exclusion criteria." (PMID 23527212, 2013). "In general, the MMP-1 -1607 2G/2G homozygote was significantly associated with an increased risk of periodontitis compared with wild-type homozygote (1G/1G) (OR = 1.50, 95% CI = 1.02–2.20)." (PMID 23527212, 2013). "Since 2003, there have been 11 studies focusing on the relationship between the SNP at position -1607 of MMP-1 and periodontitis susceptibility." (PMID 23527212, 2013). "The pooled results showed significant association between periodontitis susceptibility and MMP-1 g.-1607dupG polymorphism in homozygote (2G/2G versus 1G/1G, OR = 1.50, 95% CI = 1.02–2.20) and dominant model analysis (2G/2G+2G/1G versus 1G/1G, OR = 1.28, 95% CI = 1.04–1.57)." (PMID 23527212, 2013). "Meta-analysis for MMP-1 g.-1607dupG polymorphism and periodontitis risk." (PMID 23527212, 2013). "Relevant literatures concerning relationships between MMP-1 polymorphisms and periodontitis." (PMID 23527212, 2013). "The guanine addition at the -1607 position, the substitution of guanine for adenine at position -519 as well as the adenine to thymidine mutation at position -442 of the MMP-1 gene promoter were supposed to be the functional polymorphisms associated with periodontitis." (PMID 23527212, 2013). "Odds ratio (OR) and 95% confidence interval (CI) were used to evaluate the association between MMP-1 g.-1607dupG and periodontitis susceptibility, while Q test and Egger’s test were adopted respectively to assess heterogeneity among studies and publication bias." (PMID 23527212, 2013).
periodontitis (continued). "PFBE also downregulated the F. nucleatum-induced gene and protein expression of MMP-1, a key enzyme involved in degrading soft and hard tissues and significantly elevated in periodontitis." (PMID 40426961, 2025). "MMPs, specifically collagenase (MMP-1) and gelatinase (MMP-9), have been implicated in the progression of periodontitis." (PMID 40007939, 2025). "Statistical analysis indicates that MMP1 levels were significantly higher in gingivitis sites compared to healthy sites (p = 0.003) and peaked in periodontitis sites, with a p-value of 0.003 when compared to gingivitis." (PMID 41303313, 2025). "In gingival crevicular fluid (GCF), the concentrations of MMP1 were measured as follows: 223.26 pg/mL in healthy sites, 401.77 pg/mL in gingivitis sites, and 457.02 pg/mL in periodontitis sites." (PMID 41303313, 2025). "Certain bacteria in subgingival plaques appear to be minimally affected by the factors associated with gingivitis and periodontitis, despite most bacteria exhibiting correlations with IL-1β, endotoxins, TLR-SEAP, TLR-ATP, PAD, MMP-1, MMP-9, GBI, and MGI." (PMID 41303313, 2025). "According to a previous study, protein expression levels of MMP-1, -8, and -13 are higher in periodontitis patients than in normal controls." (PMID 36661522, 2023). "Similar alterations were observed in the longitudinal experimental periodontitis model across all age groups with elevated MMP1, MMP3, MMP9, and ALPL." (PMID 38098978, 2023). "The upregulation of TGF-β results in collagen production and reduces collagen-destroying MMP-1 production, which will be beneficial to protect against periodontitis." (PMID 35046930, 2021). "In periodontitis, MMP1, which is a collagenase, plays a key role in periodontal soft tissue destruction and alveolar bone loss." (PMID 33513808, 2021). "Several polymorphisms were associated with periodontitis, including the Fc-γ receptor, ILs-1,4,6,10,18, TNF-α, vitamin D receptor, cluster of differentiation-14, MMP-1, Toll-like receptor-2 and 4, and COX-2." (PMID 33340075, 2021). "There seems to be a significant increase in MMP expression and activity in chronic periodontitis, especially MMP-1, MMP-3, MMP-7, MMP-8, and MMP-9, with minor contributions from MMP-13 and MMP-14." (PMID 32650590, 2020). "Pirhan and colleagues aimed to examine the effect of MMP-1 (-519 A/G; -1607 1G/2G) in a Turkish population with chronic periodontitis." (PMID 28624837, 2017). "MMP-1 −1607 1G/2G, located on 11q22-q23 chromosome, is one of the most studied SNPs in periodontitis." (PMID 27194818, 2016). "The association between gene polymorphisms in chronic periodontitis and response to treatment was examined in patients that presented a susceptible genotype in the following genes IL-1, IL-4, IL-8, MMP-13, MMP-1 and MBL." (PMID 26595831, 2016). "From these data we conclude that MMP-1 secreted by PDL cells contributes to the tissue destruction seen in periodontitis and gingivitis and that hypoxia further aggravates the effects of LPS-PG on MMP-1 expression." (PMID 25861162, 2015). "In sum, the definite role of MMP-1 g.-1607dupG in the development of periodontitis remains controversy." (PMID 23527212, 2013). "Since MMP-1 and CCL2 are molecules known to be strongly associated with periodontitis, we further studied their regulation by NAMPT." (PMID 24058270, 2013). "Following the 24 months of treatment with the regimen, the regimen was found to directionally reduce bacterial amount and diversity while also statistically significantly reducing critical biomarkers (IL-1β, MMP-1, MMP-9) associated with inflammation and periodontitis." (PMID 41303313, 2025). "Visfatin may play a role in periodontitis by upregulating MMP-1 and chemokine-2 in periodontal ligament cells." (PMID 38698364, 2024). "Excessive production of MMP-1 can accelerate matrix degradation in periodontitis." (PMID 36661522, 2023).